ATM (ATM serine/threonine kinase)
Diseases named in the same sentence as ATM in open-access papers (continued):
Sharing a sentence is not in itself a finding about the gene and the disease.
lung carcinoma (continued). "ATM is a phosphatidyl inositol 3 kinase-like kinase that plays a key role in initiating DSB repair, and is a known cancer susceptibility gene that is mutated in 5% of all cancers, including 40% of mantle cell lymphomas, 20% of colorectal cancers and 10% prostate and lung cancers." (PMID 39994444, 2025). "In summary, we provide a proof-of-concept strategy that ATM inhibitors combined with TOP2 poison would synergistically suppresses lung cancer cell survival as well as reduce DNA damage responses, thus may lowering the possibility of cardiotoxicity and secondary malignancy linked to therapy." (PMID 36650267, 2023). "Furthermore, DDR mutations, such as ATM, PTEN, MRE11, and FANCA mutations, have been found in a large proportion of lung cancer patients, as well as BRCA1/2 mutations in 5% of patients, justifying the administration of PARP inhibitors to lung cancer patients." (PMID 37682974, 2023). "In summary, we provide a new approach that ATM inhibitors combined with TOP2 poison would synergistically suppresses lung cancer cell survival as well as reduce DNA damage responses, thus may lowering the possibility of cardiotoxicity and secondary malignancy linked to therapy." (PMID 36650267, 2023). "To further elucidate whether ATM downregulates PD-L1 via JAK1,2/STAT3 pathway, we generated ATM-overexpression A549CisR and H157CisR cells (A549CisR-ATM and H157CisR-ATM) and confirmed that ATM-overexpression increased the expression of PD-L1 expression in lung cancer cells." (PMID 30961670, 2019). "Moreover, several ATM polymorphisms are risk factors for developing lung cancer in never smokers with low levels of carcinogen exposure." (PMID 30093964, 2018). "Two of these studies were excluded because no other studies referred to the same polymorphism (for example, there was only one study on the association between the ATM gene rs373759 and susceptibility to lung cancer), and they were therefore not suitable for inclusion in this meta-analysis." (PMID 29246212, 2017). "Then, we performed co-immunoprecipitation experiments using total cell extracts from lung cancer cell lines of different origin (A549, H460, and H1299), expressing detectable amounts of both ATM and RanBP9 proteins, plus or minus exposure to IR to activate the ATM kinase." (PMID 26943034, 2016). "The frequency of loss of ATM protein has not been reported in lung cancer previously." (PMID 27259260, 2016). "Thus, up to 7 % of lung adenocarcinomas that have acquired somatic mutations that inactivate ATM may respond extremely well to radiotherapy, while lung cancers that express functional ATM are anticipated to be radiosensitized by ATM kinase inhibitors." (PMID 26438152, 2015). "Thus, the high phosphorylation level of ATM contributing to IL-6 correlated lung cancer metastasis indicates that the functions of ATM might be dependent on cell stress, DNA damage and signaling networks." (PMID 26528698, 2015). "However, little is known about ATM protein expression in primary lung cancer tissues." (PMID 22348039, 2012). "Integrated interpretation supports DDR/ATM → PI3K/Akt–MAPK activation with EMT/adhesion remodeling, angiogenic signaling, and immune modulation—linking residential radon to lung cancer mechanisms." (PMID 41441242, 2025). "In fact, it has been reported that SIRT7 interacts with ATM, a key regulator of the NPM–ARF pathway in lung cancer cells." (PMID 38870055, 2024).
lung carcinoma (continued). "We assessed the endogenous radioresistance levels of lung cancer cells by colony formation assays and compared them with the phosphorylation levels of RAD50 and ATM, key components of the DDR activation after radiation." (PMID 39408794, 2024). "It has been proved in lung cancer cell lines and glioblastoma cell lines that miR-101 can bind to the 3′-UTR of DNA-PKCs or ATM mRNA to negatively regulate DNA-PKCs and ATM mRNA." (PMID 36497343, 2022). "ATM was also found to be relevant to the development of DDP resistance; in contrast, knockdown of ATM can enhance the sensitivity of lung cancer cells and endometrial cancer cells to DDP." (PMID 35303867, 2022). "Following the inhibition of ATM, the processes of EMT and tumor metastasis in drug-resistant lung cancer cells are inhibited." (PMID 36213837, 2022). "The results indicate that JAK/STAT signaling is a mediator of ATM promoting EMT and metastasis in lung cancer cells." (PMID 35559037, 2022). "Specially, the ATM inhibitor AZD1390 is optimized for penetration of the blood-brain barrier with radiosensitizing effects on glioma and lung cancer cell lines, even in a brain metastasis model." (PMID 35875060, 2022). "CAF from non–small cell lung cancer (NSCLC) and head and neck (HNSCC) showed ATM activation in vitro, which correlated with SMA expression (Spearman correlation = 0.96, P = 0.0028)." (PMID 36353752, 2022). "The protein expression levels of Cyclin E, cdc25A, ATM, p21, RRM2, γH2AX, and ATR/pATR were assessed via immunoblotting on samples from exponentially growing, untreated U2OS and lung cancer cells." (PMID 34359691, 2021). "The upregulated PD-L1 expression in osteosarcoma, lung cancer, and prostate cancer in response to DSB required the activation of STAT1/3–IRF1 signaling pathway by ATM/ATR/Chk1 kinases." (PMID 34088360, 2021). "POLQ, BRCA2, ATM, ATR, PARP4, and POLD1 alterations were most commonly observed in the entire advanced lung cancer cohort." (PMID 34604048, 2021). "In this study, we investigated the roles of ATM and EMT in cisplatin-resistance and cancer metastasis in lung cancer cells." (PMID 30961670, 2019). "Thus, ATM may be a potential target for the treatment of cisplatin-resistant lung cancer." (PMID 30961670, 2019). "Collectively, these results indicate that miR‐18a‐5p increases the radiosensitivity in lung cancer cells and CD133+ stem‐like cells via downregulating ATM and HIF‐1α expressions." (PMID 29860718, 2018). "TNF-α IHC determination of lung cancer metastasis test showed that TNF-α expression in cancer nests and surrounding tissues was decreased by the depletion of ATM." (PMID 27556690, 2016). "The synthetic lethal interaction between ATM and MEK in lung cancer cells identified here indicates that these two kinases are functionally tightly linked." (PMID 27922010, 2016). "Here, we found that TNF-α promote lung cancer metastasis by MMP-13 up-regulation and ATM activation." (PMID 27556690, 2016). "Inactivation of TNF-α-ATM-ERK/p38-NF-κB decrease lung cancer metastasis, providing advanced evidences for ATM inhibitor usage in lung cancer treatment." (PMID 27556690, 2016). "This applies for fibroblasts with a defect in ATM and Artemis, as well as human lung, breast, glioma and HNSCC cells and also for xenografts of lung cancer and HNSCC." (PMID 26799421, 2016). "In the present study, we demonstrated that the activation of ATM-ERK/p38-NF-κB, which induced by TNF-α in autocrine or paracrine manner, up-regulate MMP-13 expression and thereby augment lung cancer metastasis." (PMID 27556690, 2016). "In this model, ATM is the key up-steam regulator of TNF-α activated ERK/p38-NF-κB pathway, which play a vital role in promoting lung cancer cell migration by up-regulating MMP-13 expression." (PMID 27556690, 2016).
lung carcinoma (continued). "Together, these results demonstrate that ATM-ERK/p38-NF-κB play important roles in TNF-α up-regulating MMP-13 expression and promoting lung cancer cell migration." (PMID 27556690, 2016). "The results of our western blotting revealed that the presence of caffeine caused a decrease of CHK1 phosphorylation at Ser317/Ser345 but an increase of ATM phosphorylation at Ser1981 in the cisplatin-treated HTB182 and CRL5985 lung cancer cells." (PMID 25937999, 2015). "Our previous studies demonstrate that ATM phosphorylation and elevated IL-6 level contribute to chemotherapeutic agents-inducing MDR formation in lung cancer." (PMID 26528698, 2015). "Then, the inhibition of ATM phosphorylation abolishes IL-6 increased expression of MMP-3/MMP-13, hence abrogates IL-6 correlated lung cancer metastasis both in vitro and in vivo." (PMID 26528698, 2015). "It is possible that gemcitabine-induced ATM serine 1981 phosphorylation is both ATM and ATR kinase-dependent in these lung cancer cell lines and that inhibition of either kinase is insufficient to significantly reduce the phosphorylation." (PMID 26438152, 2015). "Analyses of ATM serine 1981 and Chk1 serine 345 phosphorylation, and FANCD2 monoubiquitination revealed that ATM and ATR kinase activation and FA pathway signaling are intact in the lung cancer cell lines examined." (PMID 26438152, 2015). "Here, we investigated the role of ATM phosphorylation in IL-6 increasing MMP-3/MMP-13 expression, but the exact mechanism by which MMP-3/MMP-13 promoting lung cancer metastasis is still to be clarified." (PMID 26528698, 2015). "The cAMP signaling system inhibits radiation-induced activation of ATM by PKA-dependent activation of PP2A, thereby augmenting radiation-induced apoptosis in part by reducing ATM-dependent activation of NF-κB in lung cancer cells and mouse lung tissue." (PMID 24568192, 2014). "Small molecules or kinase inhibitors targeting growth factor receptors and the PI3K/AKT/mTOR, Src/Stat, p38, and ATM/CHK2 pathways were extensively investigated for cancer treatment, both preclinically and clinically, including treatment for lung cancers." (PMID 22348039, 2012). "In this study, we showed that exogenous NPRL2 expression in NPRL2-negative tumor cells activated the DNA damage pathway, as evidenced by activation of ATM and NBS1 and increased γ-H2AX expression in lung cancer cells after NPRL2 treatment." (PMID 20700484, 2010). "The ATM/ATR inhibitor we used, also known as CGK-733, failed to inhibit ATM/ATR kinase activity in human lung cancer cells." (PMID 37021419, 2023). "In addition to CHO cells, we investigated the impact of ATM and ATR on the intra- S-phase checkpoint in the human lung carcinoma cell line, A549." (PMID 35886852, 2022). "A previous study revealed that ATM and ATM and RAD3-related (ATR) kinase activations are intact in lung cancer cell lines and may act as lung cancer biomarkers." (PMID 36547079, 2022). "Gαs simulates ATM activation through the Gαs-cAMP-PKA-PP2A pathway, which results in declining the ATM protein-dependent nuclear factor kappa-B (NF-κB) activation, and increasing radiation-induced apoptosis in human and mouse lung cancer cells." (PMID 35832555, 2022). "In lung cancer, the interaction of IQGAP3 with DNA repair protein Rad17 was essential for Rad17 expression and foci formation, the Mre11-Nbs1-Rad50 complex formation, and ATM/Chk2 and ATR/Chk1 pathways activation." (PMID 36275458, 2022).
lung carcinoma (continued). "Chen and colleagues found that the inhibition of ATM using specific ATM inhibitor CP466722 or siRNA reduced JAK/STAT3 signaling and PD-L1 expression, thus inhibiting the EMT and metastatic potential of cisplatin-resistant lung cancer cells." (PMID 36559280, 2022). "In contrast, blood cell traits and hematological diseases were implicated with a wider range of loci, including TERC, TERT, SENP7, ATM, BBOF1, and MROH8; this result is similar to those for the respiratory function and lung cancers that also involved multiple TL loci." (PMID 32109421, 2020). "In this study, we further investigated the role of ATM in EMT and metastasis of lung cancer cells." (PMID 30961670, 2019). "Importantly, inhibition of ATM suppressed EMT and tumor metastasis in cisplatin-resistant lung cancer cells in an orthotopic xenograft mouse model." (PMID 30961670, 2019). "As miR‐18a‐5p inhibited both ATM and HIF‐1α in the present study, miR‐18‐5p could be a promising target to improve radiosensitivity in lung cancer." (PMID 29860718, 2018). "Here, we demonstrate that ATM is the PIKK that phosphorylates Hsp90α in response to ionizing radiation (IR) at T5/7 residues in head and neck squamous cell carcinoma cells, lung cancer cells, lung fibroblasts, ATM knockdown and reconstituted cells and mouse embryonic fibroblasts (MEF)." (PMID 27738310, 2016). "Together these experiments demonstrate that ATM inactivation by shRNA knockdown or CRISPR/Cas9 knockout strongly sensitizes lung cancer cells to MEK inhibition even in the absence of KRAS or BRAF mutations." (PMID 27922010, 2016). "Moreover, cisplatin and camptothecin-induced BCRP and MRP2 upregulation can be suppressed by ATM inhibitors, indicating the role of ATM activation on MDR formation in lung cancer chemotherapy." (PMID 27057637, 2016). "Moreover, the inhibition of ATM phosphorylation not only abrogates IL-6 increased, MMP-3/MMP-13 mediated cell migration in vitro, but also suppresses IL-6 correlating lung cancer metastasis in vivo." (PMID 26528698, 2015). "All together, these data suggest that ATM could be activated by the treatment with IL-6, hence increases the expression of MMP-3/MMP-13 and promotes lung cancer metastasis." (PMID 26528698, 2015). "To further define a mechanism through which the presence of triptolide causes an increase of cisplatin-induced caspase-3 activation in A549 and HTB182 lung cancer cells, we determined the effect of triptolide on cisplatin-induced CHK1 phosphorylation at Ser317/345 and ATM phosphorylation at Ser1981." (PMID 26161259, 2015). "Similar amounts of lung cancer cells suffered from ATM inhibition anchored in the vessels of the lungs (data not shown)." (PMID 26528698, 2015). "We undertook functional analyses of ATM, ATR, Chk1 and FA proteins in lung cancer cell lines." (PMID 26438152, 2015).
lung carcinoma (continued). "The results of our protein phosphorylation studies further revealed that the presence of caffeine caused a decrease in CHK1 phosphorylation at Ser317/Ser345 but an increase in ATM phosphorylation at Ser1981 in the cisplatin-treated HTB182 and CRL5985 lung cancer cells." (PMID 25937999, 2015). "Two patients (P003 and P006) who met Amsterdam criteria, whose families suffered from colorectal cancer, lung cancer and bladder cancer, were not identified as MMR mutation carriers, but they carried many other tumor-associated genes, such as BRCA2, CDH1, MET, ATM, NF1." (PMID 35372080, 2022). "Additionally, EGFR, MGA, SMARCA4, ATM, RBM10 and KDM5C which are lung cancer related genes are mutated only in LUAD but not in LUSC." (PMID 33672117, 2021). "In addition, the results of our protein phosphorylation studies indicated that the presence of triptolide reduced cisplatin-induced CHK1 phosphorylation at Ser317/345 but increased cisplatin-induced ATM phosphorylation at Ser1981 in both A549 and HTB182 lung cancer cells." (PMID 26161259, 2015). "Therefore, it is likely that inhibiting the CHK1 phosphorylation and increasing the ATM phosphorylation play important roles in the mechanism through which the presence of low-levels of triptolide potentiates both A549 and HTB182 lung cancer cells to cisplatin-induced apoptosis." (PMID 26161259, 2015). "All these findings demonstrate that IL-6 inducing ATM activation increases the expression of MMP-3/MMP-13, augments the abilities of cell migration and promotes lung cancer metastasis, indicating that ATM is a potential target molecule to overcome IL-6 correlated lung cancer metastasis." (PMID 26528698, 2015). "Lung cancer cells are radiosensitized by pharmacologic ATM kinase inhibitors in tissue culture, and it is widely believed that ATM kinase inhibitors will be well-tolerated in the clinic as ATM is not an essential protein." (PMID 26517239, 2015). "We found that cAMP signaling inhibits radiation-induced activation of ATM by PKA-dependent activation of PP2A, and the cAMP signaling system augments radiation-induced apoptosis partially by reducing the ATM-dependent activation of NF-κB in human lung cancer cells and mouse lung." (PMID 24568192, 2014). "However, it has not been studied whether ATM inhibitors combined with TOP2 poison are effective in treating lung cancer." (PMID 36650267, 2023). "To evaluate the potential role of RanBP9 in the regulation of ATM-dependent activation of the DDR, we generated stable clones from three lung cancer cell lines expressing a negative control shRNA or a RanBP9-silencing shRNA." (PMID 26943034, 2016). "No defects in ATM, ATR or Chk1 kinase activation, or FANCD2 monoubiquitination were identified in the lung cancer cell lines examined, including Calu6, and major alterations in these pathways were not identified in the TCGA database." (PMID 26438152, 2015).